UCP2 (uncoupling protein 2)
Diseases named in the same sentence as UCP2 in open-access papers (continued):
Sharing a sentence is not in itself a finding about the gene and the disease.
diabetes (continued). "Longitudinal studies tracking UCP2 levels during progression from prediabetes to overt diabetes are lacking, making it impossible to determine whether UCP2 upregulation is a primary driver of β-cell failure or a compensatory (albeit insufficient) antioxidant response to chronic oxidative stress." (PMID 41369350, 2025). "Thus, the important question concerning whether an association exists between these UCP2 genotypes and LTL remains unanswered in those without insulin resistance and/or diabetes." (PMID 27615599, 2016). "However, this may to be a kidney specific mechanism since although whole-body oxidative stress, indicated by circulating MDA-levels was increased in diabetes, it was not significantly reduced by siRNA to UCP-2." (PMID 22768304, 2012). "Nonetheless, although UCP2 expression was not change, GDP did not modify ∆ψ at 7 and 20 days of diabetes, implying that UCP2 is not active and that other mechanisms participate in ∆ψ modulation, perhaps the permeability transition pore and/or adenosine nucleotide translocator (ANT)." (PMID 25951172, 2015).
type 2 diabetes (55 papers, 2005 to 2025). "And UCP2 was most associated with cell cycle, primary immunodeficiency, type II diabetes mellitus, FcεRI signaling pathway and T cell receptor signaling pathway in Normal-like, Luminal A, Luminal B, Her2-enriched and Basal-like subtypes, respectively." (PMID 35874806, 2022). "In humans, genetic variations of Ucp2 and Ucp3 have been associated with abdominal obesity, type 2 diabetes, and increased serum lipid levels." (PMID 32452516, 2020). "The ucp2 promoter polymorphism modulates lipid levels in patients with type 2 diabetes and the presence of the A-allele contributes to the increased UCP2, decreased ADP/ATP ratio, and decreased GSIS in glucose-tolerant subjects." (PMID 29351723, 2018). "UCP2 polymorphisms are associated with leukocyte telomere length (LTL) in Type 2 Diabetes, which also induces considerable background oxidative stress." (PMID 27615599, 2016). "A recent meta-analysis has showed that the UCP2 -866G/A polymorphism is unlikely associated with increased type 2 diabetes risk in the Asian and European descent." (PMID 23537071, 2013). "The major finding of this study is that the interaction between type-2 diabetes and UCP2 G-866A genotype was significantly associated with survival in a cohort of post-MI patients." (PMID 19527523, 2009). "Uncoupling protein 2 (UCP2) inhibits glucose stimulated insulin secretion, and models of type 2 diabetes are associated with increased expression in islets." (PMID 17397545, 2007). "Knockout of UCP2 in pancreatic β-cells enhances glucose-induced insulin secretion, while its overexpression inhibits this process, increasing the risk of type 2 diabetes in humans." (PMID 40686867, 2025). "Additionally, one study showed that UCP2 variants (G174D and A268G) promoted insulin secretion, while another indicated that the UCP2 T/T variant increased the risk of type 2 diabetes." (PMID 39707176, 2024). "Finally, results from a human study on ethnicity differences in UCP2 polymorphisms demonstrated that in Asians, the UCP2-866G/A polymorphism is protective against, while the UCP2 Ala55Val polymorphism is susceptible to, type 2 diabetes." (PMID 35323702, 2022). "Human genetic studies consistently demonstrate the effect of UCP2 alleles on type-2 diabetes." (PMID 16968550, 2006). "Consistent with its potential homeostatic role in metabolic function, UCP2 overexpression has been linked to both α- and β-cell dysfunction, and increased mRNA transcripts for UCP2 have been detected in the pancreatic islets of several animal models with type 2 diabetes." (PMID 35628447, 2022). "Uncoupling protein 2 (UCP2), a mitochondrial protein, is known to be upregulated in pancreatic islets of patients with type 2 diabetes (T2DM); however, the pathological significance of this increase in UCP2 expression is unclear." (PMID 35800776, 2022). "For example, UCP2 acts as a vital link between islet β-cell dysfunction and type 2 diabetes as a negative regulator of insulin secretion." (PMID 36266633, 2022). "Several functional UCP2 models have been proposed, which include roles in beta cell pathology and consequent development of Type 2 diabetes, and in protecting beta cells against oxidative stress." (PMID 25482405, 2015). "A recent study established an additive interaction for the association between increased type 2 diabetes mellitus (T2DM) risk and the PGC-1α 1444A, UCP2 866G and ND3 10398A genotypes." (PMID 21595954, 2011). "If UCP2 is to be considered a therapeutic target in type 2 diabetes, it seems essential to shed light on these disparate findings." (PMID 21172424, 2011). "Genipin, an extract from Gardenia jasminoides, is a traditional Chinese remedy for type 2 diabetes that inhibits UCP2-mediated proton leak." (PMID 21712825, 2011). "The aim of this study was to explore the relationship between the G(-866)A polymorphism of UCP2 and hs-CRP plasma levels in type 2 diabetic patients." (PMID 21029457, 2010).
type 2 diabetes (continued). "This study extends this evidence to include UCP2 genotype as a potential marker of prognosis in type-2 diabetes patients following acute MI." (PMID 19527523, 2009). "The data presently available suggest that UCP2 up-regulation has opposing effects on different components of type-2 diabetes." (PMID 16968550, 2006). "Current data suggest that UCP2 plays a role in the metabolic syndrome through down-regulation of insulin secretion and development of type-2 diabetes." (PMID 16968550, 2006). "Finally, it is worth noting that Mito-G was specifically engineered to accumulate within pancreatic β-cell mitochondria to suppress UCP2-driven autoinflammation in type 2 diabetes." (PMID 41300438, 2025). "Additionally, miR-214 and lncRNA TUG1 regulate UCP2 expression levels and play pivotal roles in insulin resistance and type 2 diabetes." (PMID 39707176, 2024). "Increased UCP2 expression can cause a lack of glucose effect on insulin secretion in type 2 diabetes." (PMID 35323702, 2022). "Consistent with its potential homeostatic role in metabolic function, UCP2 over-expression has been linked to both α and ß-cell dysfunction and increased mRNA transcripts for UCP2 have been detected in the pancreatic islets of several animal models with type 2 diabetes." (PMID 33763373, 2021). "Thus, for example, variation in the UCP2–ucp3 gene cluster predicts the development of type 2 diabetes in healthy middle-aged men." (PMID 29351723, 2018). "This acute regulatory effect of UCP2 on beta cell function is consistent with the relatively strong GSIS exhibited by the first-established Ucp2-ablated mouse strain, which suggested a pathological role for UCP2 in the development of beta cell dysfunction and Type 2 diabetes." (PMID 25482405, 2015). "Meanwhile, the UCP2 -866G/A polymorphism is not a candidate for susceptibility to type 2 diabetes in any ethnic population." (PMID 23560041, 2013). "In addition, high-glucose reduced phosphorylation of PKA and increased UCP2 level in pancreatic islets of animal models of type 2 diabetes." (PMID 23607427, 2013). "Having established that UCP-2 is upregulated under conditions present in type-2 diabetes (high glucose concentrations and free fatty acid concentrations) we sought to establish if the endogenous UCP-2 protein expressed in human islets plays a role in insulin secretion." (PMID 18167556, 2008). "Taken together these data suggest that the chronically increased glucose and fatty acid concentrations typically present in type-2 diabetes would have an additive effect to increase the expression of UCP-2 protein in islets, an effect that would be expected to attenuate GSIS." (PMID 18167556, 2008). "UCP2 is a regulator of insulin secretion and it is proposed that increased expression of UCP2 in pancreatic β-cells results in chronic down-regulation of glucose stimulated insulin secretion leading to β-cell dysfunction and the development of type-2 diabetes." (PMID 16968550, 2006). "UCP2 expression is increased in type 2 diabetes mellitus (T2DM), where it inhibits insulin secretion from pancreatic β-cells." (PMID 35629388, 2022). "A common UCP2 promoter polymorphism -866G/A has been shown to increase transcriptional activity by allowing for easier binding of the pancreatic transcription factor PAX6, increasing the risk of glucose dysregulation and type II diabetes in several human populations." (PMID 33763373, 2021). "UCP2 expression was increased in βIRKO cells and could represent one mechanism for mitochondrial uncoupling in these cells, similar to that observed in other models of type 2 diabetes." (PMID 19956695, 2009). "This increased UCP-2 expression may contribute to impaired GSIS in type-2 diabetes." (PMID 18167556, 2008). "Thus, one can demonstrate the influence of UCP2 on type-2 diabetes or BMI in an association study even without proving the underlying biochemical reaction carried out by these proteins." (PMID 16968550, 2006).
type 2 diabetes (continued). "Other authors have observed an upregulation of uncoupling protein 2 (UCP-2), an IMM protein that dissipates the proton gradient; in pancreatic islets in type 2 diabetes." (PMID 32528413, 2020). "This lack of effect is discrepant with literature that suggests UCP2 expression is relatively high in palmitate-exposed insulinoma cells as well as in islets from mouse models of Type 2 diabetes and lipotoxicity, and in islets of Type 2 diabetic patients." (PMID 25482405, 2015). "Our previous meta-analyses indicate that the UCP2 Ala55Val and UCP3 -55C/T polymorphisms are type 2 diabetes susceptibility loci in populations of Asian, but not European descent." (PMID 23560041, 2013). "In contrast, further results indicate that the UCP2 Ala55Val and UCP3 -55C/T polymorphisms may indeed be risk factors for susceptibility to type 2 diabetes in individuals of Asian descent, but not in individuals of European descent." (PMID 23537071, 2013).
breast carcinoma (41 papers, 2011 to 2025). "One of the most studied is UCP2, which is associated with different malignant tumors, including breast cancer." (PMID 40362341, 2025). "It restrained UCP2 expression, extended ROS production, increased SODs accumulation, induced G0/G1 arrest, and caused anti-proliferation in breast cancer MCF-7 cells." (PMID 34381775, 2021). "iv, strongly elevated UCP2 levels have been linked to poorly differentiated breast cancer, indicating that similar as MCU also UCP2 helps breast cancer cells to proliferate, migrate and invade." (PMID 29113301, 2017). "In human studies, most of the results point to UCP2 potentially being associated with the development of colon and breast cancer." (PMID 21954358, 2011). "Besides, the results of the presented study showed that UCP2 was most strongly associated with a good prognosis in Basal-like breast cancers among the different molecular subtypes." (PMID 35874806, 2022). "Overexpression of UCP2 was linked to activation of the PI3K-Akt-mTOR pathway, and this was linked to endocrine resistance in ER+ breast cancer." (PMID 40190354, 2025). "Inhibition of UCP2 in UCP2-overexpressing breast cancer cells (MCF7 UCP2) by genipin resulted in a reduction in UCP2 tumorigenic properties, reduced cell proliferation, clonogenic survival and matrigel invasion." (PMID 40003568, 2025). "The presence of a response element to (-)-epicatechin in the human UCP2 promoter revealed that the inhibition of this gene in MDA-MB-231 breast cancer cells occurred at the transcriptional level." (PMID 40362341, 2025). "The treatment of MDA-MB-231 breast cancer cells with flavonoids (IC50 = 350 μM) resulted in a decrease in UCP2 gene expression, which was observed from 48 to 72 h of incubation with the flavonoid." (PMID 40362341, 2025). "In this study, we show the downregulation of UCP2 gene expression by (-)-epicatechin in MDA-MB-231 breast cancer cells." (PMID 40362341, 2025). "In vitro and in vivo studies showed that the overexpression of UCP2 promotes breast cancer tumorigenesis." (PMID 39201646, 2024). "UCP2 (uncoupling protein 2), an inner mitochondrial membrane protein, can promote autophagy and endocrine resistance in breast cancer via the ROS1 (ROS proto-oncogene 1, receptor tyrosine kinase)–AKT1 (AKT serine/threonine kinase 1)–MTOR signaling pathway." (PMID 39684286, 2024). "The high expression of UCP2 is reported to be correlated with a worse prognosis in breast cancer patients." (PMID 39195531, 2024). "This study highlighted the role of UCP-2 as a potential target to overcome drug resistance in HER2-positive breast cancer." (PMID 36900198, 2023). "A clinical trial study revealed that HER2-positive breast cancer patients had overexpressed UCP-2 in tumor samples receiving the trastuzumab drug." (PMID 36900198, 2023). "In contrast, Genipin, by decreasing UCP2 expression in MCF7 breast cancer lines, inhibited tumor promotion characterized by lower cell proliferation and migration compared to control." (PMID 36499405, 2022). "Genipin inhibits the growing of cisplatin and tamoxifen-sensitive MCF-7 and T47D breast cancer cells by inhibiting UCP2 and inducing apoptosis and autophagy." (PMID 35628447, 2022). "Bioinformatics analyses of the Cancer Genome Atlas (TCGA) database of breast cancer and melanoma patients showed a positive correlation between UCP2 expression and antitumor immune infiltration." (PMID 36499405, 2022). "A recent report indicated that inhibition of UCP-2 increased oxidative stress and sensitized breast cancer cells to tamoxifen treatment, suggesting UCP-2 as a new therapeutic target in estrogen receptor positive breast cancer." (PMID 34146128, 2021). "UCP-2 expression was significantly elevated in surgical tumor samples from breast cancer patients receiving trastuzumab in a neoadjuvant setting." (PMID 34146128, 2021).
breast carcinoma (continued). "In contrast to this, selenocysteine decreased the antioxidant enzyme and UCP2 protein expression, thereby increasing the ROS production and decreasing the viability of breast cancer cells." (PMID 33935708, 2021). "Ketone bodies are reported to suppress growth of colon and breast cancer cell lines through over-expression of uncoupling protein-2." (PMID 32343721, 2020). "Inhibition of UCP2 and UCP3 increased ROS formation, reduced viability via autophagic cell death, and increased the toxic effects of chemotherapeutics in breast cancer cells while high UCP2 levels confer a poor prognosis to breast cancer patients." (PMID 33520711, 2020). "In breast cancer cells, TGFβ has been shown to regulate expression of mitochondrial uncoupling protein 2 (UCP2), a mitochondrial transporter involved in dissipation of the mitochondria membrane potential to facilitate heat production." (PMID 31921174, 2019). "UCP2 over-expression has been found in some cancers, including bladder, colorectal, kidney, and breast cancer." (PMID 29254145, 2017). "Suppression of UCP2 by genipin, a plant derived small molecule, was shown to suppress tumorigenic properties of breast cancer cells, mediated by a decrease of ROS and downregulation of UCP2." (PMID 27766946, 2016). "UCP-2 overexpression in breast cancer cell line MCF-7 promoted their cell proliferation and induced the resistance to Doxorubicin in vitro and in vivo, which was attenuated by restoration of miR133a." (PMID 26107945, 2015). "In the present study, we aimed to explore the functional significance of miR133a-UCP-2 axis in the Doxorubicin-resistance in breast cancer cells by in vitro and in vivo cell growth studies." (PMID 26107945, 2015). "In the present study, we observed that increased expression of UCP-2 in a Doxorubicin-resistant breast cancer cell line MCF-7/Dox at both mRNA and protein level compared to its parental cell line." (PMID 26107945, 2015). "In the present study we found that lower level of miR133a is accompanied by increased expression of UCP-2 in Doxorubicin-resistant breast cancer cell cline MCF-7/Dox as compared with its parental cell line MCF-7." (PMID 26107945, 2015). "The induction of autophagy by UCP2 was further determined by the observation of punctate GFP-LC3 distribution in breast cancer cells." (PMID 26666173, 2015). "A potential correlation of miR-214 and UCP2 was observed in 20 pairs of human breast cancer tissues and matched normal tissues." (PMID 26666173, 2015). "Further studies are underway to elucidate the mechanism of UCP2-mediated autophagy in breast cancers." (PMID 26666173, 2015). "Ectopic expression of UCP2 in MCF7 breast cancer cells leads to a decreased mitochondrial membrane potential and increased tumorigenic properties as measured by cell migration, in vitro invasion, and anchorage independent growth." (PMID 24027528, 2013). "Ectopic expression of UCP2 in MCF7 breast cancer cells led to a decreased mitochondrial membrane potential and increased tumorigenic properties as measured by cell migration, in vitro invasion and anchorage independent growth." (PMID 21935467, 2011). "Eighty-six percent of grade 1, 100% of grade 2 and 93% of grade 3 breast carcinomas were positive for UCP2." (PMID 21935467, 2011). "Since the Warburg Effect relates not only to breast cancer but is a general phenomenon found in cancers, we investigated the expression of UCP2 in other cancers." (PMID 21935467, 2011). "Among several genes, our study revealed that over-expression of mitochondrial uncoupling protein UCP2 in rho0 breast epithelial cells reflects gene expression changes in breast cancer cell lines and in primary breast tumors." (PMID 21935467, 2011). "Consistent with in vitro studies, we demonstrate that UCP2 over-expression leads to development of tumors in vivo in an orthotopic model of breast cancer." (PMID 21935467, 2011).